LYAR (Ly1 antibody reactive)
Diseases named in the same sentence as LYAR in open-access papers:
LYAR is named in the same sentence as 21 diseases in open-access papers, as found by Europe PMC text mining. Sharing a sentence is not in itself a finding about the gene and the disease. The quoted sentences say what the papers report.
colorectal cancer (5 papers, 2015 to 2023). A primary or metastatic malignant neoplasm that affects the colon or rectum. "Previously, LYAR was found to be upregulated in colorectal cancer tissues, and its expression level is associated with advanced and metastatic colorectal cancer tissues." (PMID 34696677, 2021). "Previous studies have shown that LYAR promotes the migration and invasion of colorectal cancer cells by activating the expression of galectin-1." (PMID 34696677, 2021). "In tumor samples from patients with colorectal carcinoma, LYAR mRNA levels, as determined by GeneChip, were higher than those in normal cells from those patients as well as in cells from healthy subjects." (PMID 31504794, 2019). "In many of the tumor samples from cancer patients, including those with colorectal carcinoma or small-cell lung carcinoma, LYAR mRNA levels were higher than in normal tissues." (PMID 31504794, 2019). "In the present study, we demonstrate that LYAR is a novel key regulator in the progression of colorectal cancer." (PMID 26413750, 2015). "To explore the function of LYAR in colorectal cancer, we knocked-down LYAR expression in both HCT116 and HCT8 cells with two independent small interfering RNAs." (PMID 26413750, 2015). "In colorectal cancer, LYAR was shown to promote cancer progression." (PMID 36831382, 2023). "This suggested that LYAR regulates FSCN1 expression in only a subset of colorectal cancers." (PMID 35069968, 2021). "In addition, we examined LYAR mRNA levels in the low-metastasis colorectal cancer cell line SW480 and the highly metastatic line SW620 in comparison with HeLa cells." (PMID 31504794, 2019). "To address the potential molecular mechanisms by which LYAR may function in colorectal cancer invasion and metastasis, we performed a whole-genome microarray analysis of gene expression in the LYAR knockdown and scrambled control HCT8 cells." (PMID 26413750, 2015). "In addition, the heterogeneity of solid tumors makes it unlikely that upregulating the expression of LGALS1 is the only molecular mechanism by which LYAR promotes CRC migration and invasion among all colorectal cancers with high LYAR expression." (PMID 35069968, 2021).
T-cell leukemia (5 papers, 2014 to 2024). A malignant disease of the T-lymphocytes in the bone marrow, thymus, and/or blood. "LYAR (Ly-1 antibody reactive clone), a 45 kD nucleolar protein, was initially identified from a mouse T-cell leukemia line in 1993 and consists of a zinc finger motif and three nuclear localization signals." (PMID 26413750, 2015). "LYAR was originally isolated from a mouse T-cell leukemia line based on its expression of a Ly-1 epitope in a λgt11 library." (PMID 25092918, 2014). "LYAR was originally identified in a mouse T-cell leukemia line." (PMID 26413750, 2015).
neuroblastoma (4 papers, 2015 to 2023). Neuroblastoma (NB) is the most common solid, extracranial childhood tumor. "In neuroblastoma, knocking out LYAR inhibits the proliferation of neuroblastoma cells, and patients with high LYAR expression have a poor OS rate." (PMID 34696677, 2021). "In neuroblastoma, LYAR was one gene product that correlated with worse clinical outcomes." (PMID 26413750, 2015).
ovarian carcinoma (4 papers, 2014 to 2021). A malignant neoplasm originating from the surface ovarian epithelium. "A gene expression profile study with whole blood cell mRNA from ovarian cancer patients revealed LYAR and other five genes (PDIA3, NOP14, NCALD, MTSS1 and CYP1B1) as potential prognostic biomarkers for curative and postoperative supportive therapies for ovarian cancer." (PMID 26413750, 2015). "However, analysis of the whole-genome expression profile of blood cells in ovarian cancer patients showed that LYAR was one of six genes that were significantly down-regulated in the poor prognosis group." (PMID 26413750, 2015). "It has also been shown that LYAR, PDIA3, NOP14, NCALD, MTSS1 and CYP1B1 are correlated with the prognosis of ovarian cancer." (PMID 34696677, 2021). "In addition, LYAR and five other genes (PDIA3, NOP14, NCALD, MTSS1, and CYP1B1) showed potential as prognostic biomarkers for radical ovarian cancer." (PMID 34696677, 2021).
medulloblastoma (2 papers, 2020 to 2021). A malignant, invasive embryonal neoplasm arising from the cerebellum. "LYAR is a zinc finger nucleolar protein that has been implicated in cell growth, self-renewal of ESCs, and medulloblastoma." (PMID 33490242, 2020).
metastatic colorectal cancer (2 papers, 2015 to 2021). "In this study, we found that LYAR is highly expressed in CRC tissues and that the LYAR expression levels correlated with advanced-stage and metastatic colorectal cancer tissues." (PMID 26413750, 2015).
breast carcinoma (1 paper, 2022). "LYAR can enhance the stem cell-like properties of breast cancer and lead to poor prognosis of breast cancer, which is expected to be a potential biomarker for breast cancer treatment." (PMID 35571562, 2022).
disc degeneration (1 paper, 2025). "In severe disc degeneration, RCOR2, STAT3, NOTCH1, SP1, and SART1 expression were elevated, while PRIM1 and LYAR expression levels were significantly reduced." (PMID 40799650, 2025).
hepatocellular carcinoma (1 paper, 2021). A malignant tumor that arises from hepatocytes. "Cell counting kit-8, Transwell, and wound healing assay showed that knocking out LYAR significantly inhibited the proliferation, migration, and invasion of hepatocellular carcinoma cells." (PMID 34696677, 2021).
intervertebral disc degeneration (1 paper, 2025).
non-small cell lung carcinoma (1 paper, 2023). A group of at least three distinct histological types of lung cancer, including non-small cell squamous cell carcinoma, adenocarcinoma, and large cell carcinoma. "In non-small-cell lung cancer, expression of LYAR is associated with poor prognosis." (PMID 36831382, 2023).
Obesity (1 paper, 2020). Accumulation of substantial excess body fat. "Compared with the obesity group, the expression of ARG2, COX5B, and ZNT1 in the ZnSO4-treated group was significantly decreased, while the expression of LYAR and TM165 was significantly increased." (PMID 32462040, 2020).
virus infection (1 paper, 2018). "Interestingly, some LYAR proteins were found to be outside the nucleoli upon virus infection, which may be caused by IAV-induced nucleolar stress." (PMID 30209172, 2018). "Another possibility is that the RNP components directly recruit LYAR from nucleolus to nucleoplasm because they have been shown to localize to the nucleolus during virus infection." (PMID 30209172, 2018). "Moreover, we found that RNase A treatment also disrupted the interaction between LYAR and RNP components in virus-infected cells, indicating that LYAR interaction with RNP components during virus infection is mediated by RNAs." (PMID 30209172, 2018). "Further studies show that LYAR interacts with the four components of RNP in an RNA-dependent manner and also associates with the reconstituted vRNP, indicating that LYAR associates with vRNP complex during virus infection." (PMID 30209172, 2018). "Moreover, the expression of LYAR is enhanced upon virus infection, and the alteration of expression and distribution of LYAR will definitely affect LYAR functions, thereby influencing nucleolus functions, which may in turn facilitate virus replication." (PMID 30209172, 2018). "To further explore the role of LYAR in the IAV life cycle, we next investigated the progress of expression of LYAR during the course of virus infection." (PMID 30209172, 2018). "The results revealed that PA, PB1, PB2, and NP were all coprecipitated by LYAR, demonstrating a real interaction between LYAR and RNP components during virus infection." (PMID 30209172, 2018). "Additionally, LYAR can directly interact with NCL and colocalize with NPM1 in nucleoli, providing a possibility for them to form a complex during virus infection." (PMID 30209172, 2018). "We show that LYAR promotes viral RNA synthesis during virus infection but does not affect primary transcription, suggesting that LYAR facilitates genome replication and consequently additional transcription." (PMID 30209172, 2018).
cancer (14 papers, 2015 to 2024). A tumor composed of atypical neoplastic, often pleomorphic cells that invade other tissues. "We found that LYAR is highly expressed in a variety of cancers and is associated with poor prognosis." (PMID 34696677, 2021). "LYAR is identified to be associated with cytoplasmic ribosomes in male germ and cancer cells and is involved in preribosomal RNA processing within the nucleus." (PMID 32462040, 2020). "LYAR has been previously shown to associate with cancer potential, but the biological function of LYAR in cancer is poorly understood." (PMID 26413750, 2015). "We have demonstrated that LYAR could associate with cancer cell invasion and migration." (PMID 26413750, 2015). "Here, the cancer genome atlas (TCGA) was used to study the correlation between LYAR expression and overall survival (OS) rate in 33 cancers and to determine its potential function and prognostic value." (PMID 34696677, 2021). "In our study, we found that LYAR is highly expressed in a variety of cancers and is significantly related to prognosis, grade, and staging." (PMID 34696677, 2021). "Myc oncoprotein upregulates LYAR expression by activating its gene transcription, and the upregulation of LYAR, in turn, protects cancer cells against oxidative stress-mediated apoptosis through reducing CHAC1 gene expression." (PMID 32462040, 2020). "Ly1 antibody reactive (LYAR), involved in pre-rRNA processing, has the highest expression in mESCs compared to many cells including cancer cells and MEF, and is downregulated upon differentiation." (PMID 33203179, 2020). "Mouse fibroblasts overexpressing mouse LYAR cDNA contribute to tumor formation in nude mice; thus, LYAR is believed to be a nucleolar oncoprotein that regulates the growth and proliferation of cancer cells." (PMID 31504794, 2019). "LYAR is a candidate oncoprotein, so we assessed the intracellular levels of LYAR or LYAR mRNA in tissues from normal/control subjects and cancer patients." (PMID 31504794, 2019). "This study aimed to analyze the prognostic value of LYAR in cancer." (PMID 34696677, 2021). "Based on our current results and those of our previous study, we propose that upregulation of LYAR in certain cancer cells promotes rDNA transcription and pre-rRNA processing, resulting in increased ribosome biogenesis and maintenance of rapid growth and proliferation." (PMID 31504794, 2019). "To investigate whether galectin-1 was a key mediator for LYAR-promoted cancer cell invasion and metastasis, we performed rescue experiments in which galectin-1 was overexpressed in LYAR knockdown cells." (PMID 26413750, 2015). "Therefore, it will be interesting to determine whether cancer cells that express LYAR at a high level can maintain their tumorigenic potential upon suppression of LYAR function in rRNA synthesis." (PMID 31504794, 2019). "We further summarized six genes (IGF2BP3, LYAR, RALY, STAU1, SYNCRIP, and TOP1) that displayed high correlations between mRNA and protein expression in both cancer and cell line databases." (PMID 36428700, 2022). "We previously reported that cancer cells, such as HeLa and MCF7, have reduced ribosome production and proliferation when the level of LYAR is low; when the level of LYAR is elevated, however, cell proliferation increases." (PMID 31504794, 2019). "Our present findings concerning the potential interactions among LYAR/UBF, LYAR/BRD2-KAT7-JADE3 and/or LYAR/BRD4-KAT7-JADE3 may provide other potential targets for cancer treatment." (PMID 31504794, 2019). "Levels of galectin-1 protein and levels of LYAR protein in CRC tissues exhibited a significant correlation calculated by Pearson's correlation, further indicating that LGALS1 is a potential target of LYAR in cancer cells." (PMID 26413750, 2015).
cancer (continued). "Compared with the control LYAR-KD cells, the migration and invasion potential of the HCT116 and HCT8 cancer cells overexpressing galectin-1 was significantly increased indicating that exogenous expression of galectin-1 partially restored mobile potential of LYAR-KD cells." (PMID 26413750, 2015). "Taken together, these results indicate that LYAR was highly expressed in advanced-stage and metastatic CRC patient tissues, which suggests that LYAR expression may be involved in the invasion-metastasis cascade of cancer cells in patients with CRC." (PMID 26413750, 2015). "However, aside from these, there have been no other reports on the function of LYAR in cancer." (PMID 35069968, 2021). "However, the potential function of LYAR in human cancers, including CRC, is not yet clear." (PMID 26413750, 2015).
tumor (9 papers, 2015 to 2024). "LYAR is highly expressed in tumor cells and embryonic stem cells, which are cell types that increase the production of ribosomal proteins in order to support high rates of cell proliferation." (PMID 36831382, 2023). "We further reported that LYAR promotes tumor cell migration and invasion by directly binding to the LYAR-binding motif (CTAACC; reverse complement GGTTAG) in the LGALS1 promoter to activate its expression in CRC cells." (PMID 35069968, 2021). "As a transcription factor, LYAR can transcriptionally regulate a variety of genes and promote tumor development." (PMID 34696677, 2021). "Of these genes, the cell growth-regulating protein, LYAR, was often downregulated in tumor-infiltrated lymph nodes." (PMID 34858833, 2021). "In summary, this study reveals a novel mechanism by which LYAR promotes tumor cell migration and invasion by upregulating FSCN1 expression and affecting fatty acid metabolism in CRC." (PMID 35069968, 2021). "A novel pathway for function of the transcription factor LYAR in CRC has also been revealed: LYAR promotes tumor migration and invasion by upregulating FSCN1 expression, which in turn positively regulates fatty acid metabolism." (PMID 35069968, 2021). "Subsequently, there have been very few articles related to the function of LYAR, especially in the field of tumor research." (PMID 35069968, 2021). "Mechanistically, knockdown of LINC00355 inhibited cell proliferation, migration and invasion, promoted cell apoptosis in vitro, and suppressed tumor growth in vivo through targeting miR-466, and thus down-regulated LYAR expression." (PMID 33111744, 2020). "Western blot analysis of tumor tissues from 15 patients confirmed that the LYAR expression levels in the tumor tissues were significantly higher than those in the matched adjacent normal tissues." (PMID 26413750, 2015). "In addition, we found genes associated with tumor progression were downregulated; among these were heat shock proteins (HSP), such as HSPH1, HSPD1, LYAR and EPHA2." (PMID 38992681, 2024). "We speculate that LYAR may also promote proliferation of embryonic stem cells and promote tumor development through direct transcriptional regulation of MKI67IP or recruitment of MKI67IP." (PMID 34696677, 2021). "LYAR expression was also related to tumor grade, stage, age, and tumor status." (PMID 34696677, 2021). "Moreover, knockdown of LINC00355 decreased LYAR expression to suppress the tumor growth in lung SCC via mediating miR-466 expression." (PMID 33111744, 2020). "Because LYAR accelerates the processing of pre-rRNA in cultured cells including HeLa cells, we postulated that LYAR also enhances ribosome production by accelerating rRNA synthesis in tumor cells to help maintain their rapid proliferation." (PMID 31504794, 2019). "Thus, a novel role for the transcription factor LYAR in CRC has been revealed: LYAR promotes tumor migration and invasion by upregulating galectin-1 gene expression." (PMID 26413750, 2015). "Thus, this study revealed a novel mechanism by which the transcription factor LYAR may promote tumor cell migration and invasion by upregulating galectin-1 gene expression in CRC." (PMID 26413750, 2015). "We previously found that LYAR was expressed at a higher level in metastatic CRC tissues and that it promotes tumor cell migration and invasion by upregulating LGALS1 expression in CRC cell lines." (PMID 35069968, 2021). "LYAR not only significantly promotes the migration and invasion of CRC cells in vitro, but knockdown (KD) of LYAR in CRC cells also inhibits xenograft tumor metastasis in vivo." (PMID 35069968, 2021). "Our results showed that LYAR was upregulated in HCC tissues and its expression was related to the clinical stage, grade, and vascular tumor cell type." (PMID 34696677, 2021).
tumor (continued). "In our current study, we demonstrated that LYAR directly binds to the LGALS1 gene promoter at −1359 bp to induce galectin-1 expression and to promote tumor invasion and the migration of CRC cells." (PMID 26413750, 2015). "Analysis of the expression of LYAR in different tumor cell lines in the CCLE database, showed that LYAR was expressed in multiple tumor cell lines, and the expression level was higher in the tumor cell lines than in the normal tissues." (PMID 34696677, 2021).
infection (2 papers, 2014 to 2018). The state of being infected such as from the introduction of a foreign agent such as serum, vaccine, antigenic substance or organism. "Following infection of MEL cells with LYAR shRNA lentivirus and subsequent flow cytometric sorting of GFP positive cells, a significant reduction of LYAR protein was detected by western blot." (PMID 25092918, 2014). "The data showed that the mRNA level of LYAR increased in both PR8 H1N1 and HM H5N1 virus-infected cells, which is correlated with virus replication during the infection course, suggesting that IAV infection upregulates the expression of LYAR at the transcriptional level." (PMID 30209172, 2018).
LYAR also shares sentences with these, for which no sentence is quoted: neural tube defect (1 paper); primary effusion lymphoma (1); renal cell carcinoma (1); small cell lung carcinoma (1); thalassemia (1).